LILRB4 (leukocyte immunoglobulin like receptor B4)
Diseases named in the same sentence as LILRB4 in open-access papers (continued):
Sharing a sentence is not in itself a finding about the gene and the disease.
emphysema (2 papers, 2021 to 2024). "To answer this question, we utilized LILRB4-deficient (LILRB4−/−) mice and analyzed an elastase-induced emphysema mouse model." (PMID 34425800, 2021). "The deficiency of LILRB4 exacerbated emphysematous lesions in a mouse model of emphysema." (PMID 34425800, 2021). "LILRB4 was found to be upregulated on interstitial macrophages in human chronic obstructive pulmonary disease and mouse emphysema models." (PMID 38397424, 2024). "Further examinations are needed to determine the ligand in order to understand the roles of LILRB4 and its ligand in the pathogenesis of emphysema." (PMID 34425800, 2021). "We further examined the change of expression of LILRB4 on IMs in an elastase-induced emphysema mouse model." (PMID 34425800, 2021). "We further examined the inflammatory responses and emphysematous changes in a mouse model of emphysema using both wild-type and LILRB4-deficietnt mice to surmise the role of LILRB4 in the pathogenesis of emphysematous lesions and COPD." (PMID 34425800, 2021). "In the experiments using an elastase-induced mouse model of emphysema, we also analyzed the LILRB4 expression on lung macrophages." (PMID 34425800, 2021). "Upregulation of LILRB4 may exert a protective effect against emphysema formation by decreasing the expression of matrix metalloproteinase MMP-12 in the lungs." (PMID 38397424, 2024). "This upregulated LILRB4 may have a protective effect against emphysema formation, possibly through decreasing MMP-12 expression in the lungs." (PMID 34425800, 2021). "In addition, we analyzed the changes of LILRB4 expression in an elastase-induced mouse model of emphysema." (PMID 34425800, 2021). "The correlation between the severity of emphysematous lesions and the accumulation of LILRB4-positive IMs in human lungs suggested that LILRB4 could have a role in the pathogenesis of emphysema." (PMID 34425800, 2021). "Our studies found that the percentage of LILRB4-positive cells in total lung IMs was significantly increased in both COPD patients and a mouse model of emphysema." (PMID 34425800, 2021). "In this study, we aimed to examine the changes of LILRB4 on macrophages both in the lung specimens of COPD patients and the lungs of a mouse emphysema model." (PMID 34425800, 2021). "In this study, we focused on LILRB4, one of the inhibitory immune-receptors, and tried to determine the changes in expression of LILRB4 and its roles in the pathogenesis of human COPD and the development of emphysema in mice." (PMID 34425800, 2021). "LILRB4 on interstitial macrophages was upregulated both in human COPD lungs and in a mouse model of emphysema." (PMID 34425800, 2021). "Our results suggest that LILRB4, which is upregulated on lung IMs in both human COPD patients and a mouse elastase-induced emphysema model, has a protective effect against the formation of emphysematous lesions through the attenuation of MMP-12 production, mainly by IMs." (PMID 34425800, 2021). "Our analyses of both the human lung samples and LILRB4-deficeint mice suggest that LILRB4, which is upregulated on lung IMs in COPD patients, may have a protective effect against emphysema formation through decreasing MMP-12 expression." (PMID 34425800, 2021). "Third, although fibronectin has been quite recently identified as a physiological ligand on both human monocytic leukemia cell line THP-1 cells and human primary monocytes, the existence of a pathophysiological ligand for LILRB4 on lung IMs in COPD and a mouse emphysema model remains unclear." (PMID 34425800, 2021). "Therefore, LILRB4 may have a protective effect against emphysema formation by its involvement in a negative-feedback loop." (PMID 34425800, 2021).
encephalitis (2 papers, 2022). An acute inflammatory process affecting the brain parenchyma. "Although disease progression was faster in SARS-CoV-2 infected mice, infection with both viruses resulted in neuronal infection and encephalitis with increased expression of Interferon-stimulated Irf7, Bst2, Ifi294, as well as CxCL10, CCL5, CLC2, and LILRB4, and both models were uniformly lethal." (PMID 35967447, 2022).
gastric cancer (2 papers, 2015 to 2023). A primary or metastatic malignant neoplasm involving the stomach. "LILRB4 has been associated with tumour immune-evasion with lower expression correlating with higher sensitivity to killing by NK cells in gastric cancer." (PMID 38022598, 2023). "LILRB1 and LILRB4 are also expressed on human primary gastric cancer specimens compared to healthy tissue, with high expression correlating with advanced disease." (PMID 38022598, 2023). "LILRB4 is expressed on a number of cancers, including AML, multiple myeloma, gastric cancer, melanoma, colorectal, pancreatic, hepatocellular, NSCLC and ovarian cancers." (PMID 38022598, 2023).
monocytic leukemia (2 papers, 2022 to 2025). "Similarly, leukocyte immunoglobulin-like receptor B4 (LILRB4), a member of the leukocyte Ig-like receptor superfamily, is associated with monocytic leukemia and facilitates tumor cell infiltration into tissues while suppressing T cell activity." (PMID 39987091, 2025). "LILRB4 is expressed on antigen-presenting cells and monocytic leukemia cells in both humans and mice; however, unlike mouse LILRB4, human LILRB4 is not expressed on conventional T and NK cells." (PMID 35132958, 2022).
myelodysplastic syndrome (2 papers, 2022 to 2024). A clonal hematopoietic disorder characterized by dysplasia and ineffective hematopoiesis in one or more of the hematopoietic cell lines. "This striking finding paves the way to improve the therapeutic effect of AML or myelodysplastic syndromes (MDS) in combination with FTO inhibitors or anti-LILRB4 monoantibody based on HMAs." (PMID 35720276, 2022).
systemic lupus erythematosus (2 papers, 2019 to 2024). An autoimmune multi-organ disease typically associated with vasculopathy and autoantibody production. "In addition to tumors, differential expression of LILRB4 is present in a variety of immune system diseases, such as Kawasaki disease (KD) and systemic lupus erythematosus (SLE)." (PMID 38397424, 2024).
acute lymphoid leukemia (1 paper, 2022). "Interestingly, LILRB4 is also enriched in bulk RNA-seq sample of acute lymphoid leukemia." (PMID 35771283, 2022).
acute monocytic leukemia (1 paper, 2024). Acute monoblastic leukemia (AML-M5), is one of the most common subtypes of acute myeloid leukemia (AML) that is either comprised of more than 80% of monoblasts (AML-M5a) or 30-80% monoblasts with (pro)monocytic differentiation (AML-M5b). "The immune checkpoint leukocyte immunoglobulin-like receptor B4 (LILRB4) is found specifically on the cell surface of acute monocytic leukemia (monocytic AML), an aggressive and common subtype of AML." (PMID 38235377, 2024).
Ataxia (1 paper, 2022). Ataxia refers to impaired coordination of voluntary muscle movement. "Compared with C57BL/6 WT mice, LILRB4-KO mice had more severe failure to gain weight and more pronounced signs of neurological disease, including severe ataxia and paresis/paralysis." (PMID 35132958, 2022).
atherosclerosis (1 paper, 2021). A disease characterized by the build-up of fatty material and calcium deposition in the arterial wall resulting in partial or complete occlusion of the arterial lumen. "Interestingly, the development of atherosclerosis was promoted by Lilrb4-deficient bone marrow-derived monocytes, which triggered pro-inflammatory effects by increased activation of NF-κB signaling due to decreased Shp1 phosphorylation." (PMID 34943215, 2021).
B cell deficiency (1 paper, 2021). A broad classification of disorders where circulating numbers of B lymphocytes are decreased or ineffective. "B-cell deficiency did not affect expression of IL1β nor other DAM genes, such as TNFα, Igf1, and Lilrb4." (PMID 33846335, 2021).
cardiac hypertrophy (1 paper, 2024). "Overexpression of LILRB4 in the heart attenuates cardiac hypertrophy, fibrosis and dysfunction in response to pressure overload, and it inhibits angiotensin II-induced cardiomyocyte hypertrophy in vitro." (PMID 38397424, 2024). "It has been shown that LILRB4 prevents pathological cardiac hypertrophy through SHP-2-dependent inhibition of the NF-κB pathway, and it may serve as a potential therapeutic target for cardiac hypertrophy." (PMID 38397424, 2024).
Cognitive impairment (1 paper, 2025). Abnormal cognition is characterized by deficits in thinking, reasoning, or remembering. "In summary, this study uncovers LILRB4's dual role in female PD patients: its variants may delay motor symptom progression by preserving DAT function but exacerbate cognitive deficits, underscoring the complexity of sex‐specific pathological mechanisms." (PMID 40702763, 2025). "Our findings in females further confirmed this hypothesis, showing that LILRB4 exacerbates PD‐related cognitive impairment through accumulation of both Aβ and tau." (PMID 40702763, 2025). "Last, further analyses demonstrated the LILRB4‐cognitive impairment link in females may involve compounded WMH pathology and sex‐specific glial activation patterns." (PMID 40702763, 2025). "Therefore, further studies are warranted to validate and explore the mechanisms by which LILRB4 may contribute to cognitive impairment in PD." (PMID 40702763, 2025). "Thus, we hypothesize that LILRB4 might facilitate PD cognitive impairment in PD by promoting Aβ accumulation." (PMID 40702763, 2025).
glucose metabolic disorder (1 paper, 2021). "In a high-fat diet induced NAFLD model in mice, the hepatocytes on which LILRB4 is upregulated by inflammatory stimuli showed an improvement from insulin resistance, glucose metabolic disorder, hepatic lipid accumulation, as well as inflammatory responses." (PMID 34425800, 2021).
intrahepatic cholangiocarcinoma (1 paper, 2023). A carcinoma that arises from the intrahepatic bile duct epithelium in any site of the intrahepatic biliary tree. "For example, depletion of FTO induces suppression of LILRB4 in AML, and ALKBH5 facilitates expression of PD-L1 in intrahepatic cholangiocarcinoma (ICC)." (PMID 36810281, 2023).
ischemia (1 paper, 2025). A hypoperfusion of the BLOOD through an organ or tissue caused by a PATHOLOGIC CONSTRICTION or obstruction of its BLOOD VESSELS, or an absence of BLOOD CIRCULATION. "Microglial overexpression of Lilrb4 was found to prevent ischemia‐induced brain damage." (PMID 40843131, 2025).
Lewis lung carcinoma (1 paper, 2024). "Fibronectin was recently identified as a ligand of leukocyte immunoglobulin-like receptor subfamily B member 4 (LILRB4), one of NK cells inhibitory receptors, and their interaction attenuates NK cell killing of Lewis lung carcinoma cells." (PMID 39066359, 2024).
liver cancer (1 paper, 2022). An epithelial or non-epithelial malignant neoplasm that arises from the liver. "Our study revealed that the mRNA expression of LILRB1, LILRB2, LILRB3, and LILRB5 was downregulated, while compared with normal tissues, the mRNA expression of LILRB4 was upregulated in liver cancer tissues." (PMID 35321724, 2022).
meningoencephalitis (1 paper, 2022). Inflammation of the meninges and brain, generally secondary to an infectious cause. "Here, we report that expression of LILRB4, which binds Zika virus (ZIKV), was increased in microglia and myeloid cells infiltrating the brains of neonatal mice with ZIKV-associated meningoencephalitis." (PMID 35132958, 2022). "In addition, cellular infiltration by myeloid cells and activated lymphocytes during infection contributes to the increased LILRB4 levels in meningoencephalitis." (PMID 35132958, 2022).
Miscarriage (1 paper, 2024). A pregnancy that ends at a stage in which the fetus is incapable of surviving on its own, defined as the spontaneous loss of a fetus before the 22th week of pregnancy. "A previous study reported a reduction in IL-10, Tim-3, or LILRB4 expression in dMφ in a mouse model of T. gondii-induced miscarriage." (PMID 38987795, 2024).
myeloid malignancies (1 paper, 2024). "In the long run, defining the mechanisms underlying the interaction of therapeutic antibody Fc and FcγRs as we have reported here will help us to develop therapeutics targeting LILRB4 and other immune checkpoints on myeloid malignancies with greater potency and efficacy." (PMID 38235377, 2024).
pneumonia (1 paper, 2022). An acute, acute and chronic, or chronic inflammation focally or diffusely affecting the lung parenchyma, caused by an infection in one or both of the lungs (by bacteria, viruses, fungi, or mycoplasma.). "RNA-seq confirmed significant induction of LAIR-1 and LILRB4 dominantly in “DAD2” followed by “pneumonia”." (PMID 35992303, 2022).
renal carcinoma (1 paper, 2021). A carcinoma arising from the epithelium of the renal parenchyma or the renal pelvis. "Similarly, we found the expression of LILRB4 was higher on CD4+ T cells than on CD8+ T cells within tumor-infiltrating CD3+ T cells in the mouse renal carcinoma model RENCA." (PMID 33974041, 2021).
sarcoidosis (1 paper, 2019). Sarcoidosis is a multisystemic disorder of unknown cause characterized by the formation of immune granulomas in involved organs. "The combination of these MHC variations, with the variants in the LILRB4, could alter the immune reaction in sarcoidosis and lead to self-resolving disease." (PMID 31921204, 2019). "LILRB4-HLA-G interaction has been demonstrated to limit the activation of dendritic cells, which are important APCs in sarcoidosis inflammation." (PMID 31921204, 2019).
Stroke (1 paper, 2025). Sudden impairment of blood flow to a part of the brain due to occlusion or rupture of an artery to the brain. "Recently, single-cell RNA sequencing (scRNA-Seq) identified a critical role for leukocyte immunoglobulin-like receptor B4 (LILRB4) in microglia in modulating the immune response after stroke by regulating CD8+ T cell infiltration and activation." (PMID 40650034, 2025).
Zika virus infections (1 paper, 2022). "Altered NK cells underlie the severe ZIKV infection in LILRB4-deficient mice." (PMID 35132958, 2022). "Last, while most WT mice survived the infection, 72% of LILRB4-KO mice died between 18 and 22 dpi, indicating that LILRB4 plays a key role in controlling the outcome of ZIKV infection." (PMID 35132958, 2022). "Last, flow cytometry analysis showed that during ZIKV infection, LILRB4 was expressed primarily by myeloid cells, mostly microglia (CD45int) and infiltrating myeloid cells, including macrophages, neutrophils, and CD11b+ DCs." (PMID 35132958, 2022). "To investigate how LILRB4 helps control ZIKV infection, we first tested whether mouse LILRB4 binds to ZIKV in vitro." (PMID 35132958, 2022). "This suggests that LILRB4 could play a pivotal role in regulating the local immune response and limiting the neurological damage induced by ZIKV infection and potentially be a therapeutic target to reduce tissue damage." (PMID 35132958, 2022). "LILRB4 expression is upregulated on microglia and infiltrating myeloid cells during ZIKV infection." (PMID 35132958, 2022). "Their central role in controlling ZIKV infection was confirmed by the increased viral loads and reduced survival in mice treated with anti–NK1.1 antibodies and the rescue in ZIKV-infected LILRB4-KO mice that received NK cells from WT mice." (PMID 35132958, 2022).
tumor (56 papers, 2007 to 2025). "LILRB4 is also expressed on tumor-infiltrating myeloid-derived suppressor cells (MDSCs) and tumor-associated macrophage to promote tumor progression." (PMID 38951916, 2024). "The role of LILRB4 in interacting with tumour-associated macrophages and its negative regulation of immune responses in tumours highlights its potential as a target for immunotherapy, underlining its pivotal role in modulating tumour-immune interactions." (PMID 39457550, 2024). "High LILRB4 expression has also been reported to be associated with tumour progression and poor prognosis." (PMID 36748687, 2023). "To understand the mechanisms underlying the anti-LILRB4 antibody–mediated decrease in tumor growth and increase in survival, we analyzed the effects of anti-LILRB4 monoclonal antibody treatment on both intratumoral myeloid and lymphoid cell populations." (PMID 33974041, 2021). "Metabolic pathway enrichment analysis of differentially expressed genes in these tumor cell subsets showed a strong association of LILRB4+ MM cells with nitrogen metabolism, this may be associated with high gamma globulin synthesis in MM." (PMID 41417876, 2025). "Similarly, it has been shown that LILRB4 expression is significantly elevated and supports tumor cell migration and invasion in the tumor-associated macrophages (TAMs) of many solid tumors." (PMID 38397424, 2024). "Fibronectin or galectin-8 binding to LILRB4 could enhance the suppressive phenotype of tumor-associated myeloid cells." (PMID 38951916, 2024). "Additional modalities have also been developed and tested for targeting LILRB4 in cancer therapy, including antibody drug conjugates for direct cytotoxicity of LILRB4 expressing tumor associated myeloid cells, and LILRB4 CAR-T cells for targeting LILRB4 expressing leukemic cells." (PMID 37662958, 2023). "In hematologic cancers, LILRB4 has been identified as a marker for monocytic AML and implicated in tumor cell infiltration and T-cell suppression." (PMID 40597436, 2025). "LILRB4, with its T-cell suppressive effects, also highlights the potential for immune activation and tumor control." (PMID 40597436, 2025). "Among these, Cluster 6 exhibited significant upregulation of LILRB4, whereas minimal expression was observed in the other MM tumor cell subsets." (PMID 41417876, 2025). "Both membrane-bound and soluble forms suggest that LILRB4 plays a complex role in immune regulation and tumor progression." (PMID 40597436, 2025). "By regulating cytokines like IL-6, IL-1β, and TNF, LILRB4 influenced BC incidence, tumor growth, and patient survival outcomes." (PMID 40860159, 2025). "Differential gene expression (DGE) analysis of our scRNA-seq data revealed that Lilrb4a (Lilrb4) was upregulated in the CRD-induced tumor samples." (PMID 41102383, 2025). "In order to clarify the expression of LILRB4 in primary tumor cells, we first used a single-cell dataset to analyze the expression of LILRB4 in tumor subpopulations, and performed metabolic and cell communication analysis through differential genes." (PMID 41417876, 2025). "These efforts highlight the therapeutic potential of LILRB4 targeting to reverse tumor immunosuppression and enhance antitumor immunity." (PMID 40860159, 2025). "Another study showed that LILRB4 blockade increased the proportions of tumor immune infiltrates, effector T (Teff) levels, and altered the TME toward reduced immunosuppression in solid tumors." (PMID 41102383, 2025). "We found that chronic CRD disrupted mammary gland morphology, increased lung metastasis, and induced an immunosuppressive tumor microenvironment by enhancing LILRB4 expression." (PMID 41102383, 2025). "BiKE combined with CD16A strongly activated NK cells derived from human peripheral blood, and at the same time, BiKE bridged tumor cells to NK cells and promoted NK cytotoxicity, showing significant antitumor activity against LILRB4-high MM cells." (PMID 41417876, 2025).